ALK (ALK receptor tyrosine kinase)
Diseases named in the same sentence as ALK in open-access papers (continued):
Sharing a sentence is not in itself a finding about the gene and the disease.
lung cancer (continued). "In this study, we characterized the clinicopathologic features and genetic changes associated with EGFR, KRAS, and ALK in lung cancer." (PMID 26992209, 2016). "GEMMs are also a valuable testing platform in the cases of rare lung cancer mutations, such as those affecting the ALK gene." (PMID 27350784, 2016). "In the year 2007, the fusion of echinoderm microtubule-associated protein-like 4 (EML4) genes with anaplastic lymphoma kinase (ALK) was found in lung cancer." (PMID 25706305, 2015). "EGFR mutations and ALK gene fusions are the key molecular treatment predictive alterations for targeted therapy in lung cancer today." (PMID 26124082, 2015). "Mutations in EGFR and ALK gene fusions represent current molecular treatment predictive alterations for targeted therapy in lung cancer, but rarely appear in LC or LCNEC tumors with only a few reported cases in the literature." (PMID 26124082, 2015). "The high prevalence of activating EGFR mutations (32.7%) and ALK rearrangements (6.8%) among lung cancer patients in China has further expanded the use of these targeted agents." (PMID 26220301, 2015). "The survey of this study specifically examined the diffusion of EGFR and ALK tests as the two main diagnostic lung cancer tests according to the relevant guidelines." (PMID 25562146, 2014). "In lung cancers, ALK mutations appear to develop during clinical treatment with crizotinib and their generation probably renders EML4-ALK resistant not only to crizotinib but also to other ALK inhibitors." (PMID 25083769, 2014). "EML4-ALK mutations in lung cancer that confer resistance to ALK inhibitors ALK Lung Cancer Study Group." (PMID 25628210, 2014). "Studies of ALK-rearranged lung cancers with acquired resistance to crizotinib have identified ALK fusion gene amplification and secondary ALK TK domain mutations (L1196M and G1269A) in about one third of cases." (PMID 25364578, 2014). "ALK rearrangement is rare in lung cancer with nGGOs, but is associated with advanced stage and larger tumor size, suggesting its association with aggressive progression of lung adenocarcinoma." (PMID 24885886, 2014). "Although ALK fusion proteins can coexist with other lung cancer driver mutations, these molecular double-hits are rare." (PMID 24955213, 2014). "Targeted therapies have significantly altered the landscape of oncology, for instance BRAF inhibitors in patients with BRAF-mutated melanoma and ALK inhibitors in patients with ALK-rearranged lung cancer." (PMID 25126591, 2014). "The evaluation of various diagnostic platforms for ascertainment of ALK status is an important topic in lung carcinoma, and this subject will become increasingly prominent in neuroblastoma diagnostics." (PMID 25188507, 2014). "We performed a comprehensive analysis of EGFR/KRAS mutation and ALK rearrangement in a total of 360 surgically resected lung cancers." (PMID 23936355, 2013). "In lung cancer, the fusion of ALK and echinoderm microtubule-associated protein-like 4 (EML4) leads to constitutive activation of the kinase." (PMID 24376513, 2013). "Lung cancers that harbor this mutation derive oncogenicity from the ALK tyrosine kinase activity and share common biological and pathological features." (PMID 23675251, 2012). "Inversion of the short arm of chromosome 2 is the most common rearrangement associated with the ALK gene in lung cancer." (PMID 23198868, 2012). "The Hsp90 inhibitor IPI-504 is currently in clinical trials to test its efficacy in lung cancer patients with ALK mutations." (PMID 22363766, 2012). "The R1275Q mutation of ALK is correspondingly adjacent to the most common lung cancer-associated mutation (L858R) in EGFR." (PMID 22347506, 2012).
lung cancer (continued). "More recently, translocations and mutations in ALK have been associated with lung cancer and neuroblastoma, suggesting a key function for ALK in the development of several cancers." (PMID 21799923, 2011). "Furthermore, a previously reported patient with metastatic ALK-rearranged lung cancer harboring an acquired ALK resistance mutation (ALK I1171N) showed a good response to ensartinib, with mild rash, and no further brain metastases after 3 months of follow-up." (PMID 40052122, 2025). "Using an in vitro drug screening approach, we found that ESK440 significantly inhibits proliferation of cancer cells with different types of ALK genomic aberrations such as lung cancer cells (EML4-ALK fusion) and NB cells (mutations, amplifications), as well as some of the DIPG cells." (PMID 39900433, 2025). "Detecting ALK rearrangement in ctDNA demonstrates adequate diagnostic accuracy and could serve as a highly specific test in lung cancer patients." (PMID 40853979, 2025). "Increasing evidence suggests that lung cancer patients with EML4::ALK v3 tumors may have less favorable clinical outcomes compared to patients with other EML4::ALK variants." (PMID 40041857, 2025). "This is the first description tracking the development of resistance mutations in a patient with non‐myofibroblastic sarcoma and questions the utility of the presence of G1202R mutation as a marker of lorlatinib sensitivity in non‐lung ALK rearranged tumours, contrary to experience in lung cancer." (PMID 39188081, 2024). "The preferred method of ctDNA detection is through Next-Generation Sequencing (NGS), which has become a mandatory component in lung cancer management, being a standard in the detection of ALK, EGFR, and BRAF mutations amongst many others, which helps in making treatment decisions." (PMID 39195131, 2024). "EGFR and ALK mutations are critically relevant for prediction of treatment response in lung cancer." (PMID 38572163, 2024). "Therapies for lung cancer with ALK gene mutations currently focus mainly on TKIs." (PMID 39199653, 2024). "ALK fusion mutation is one of the most important mutations in nonsmall cell lung cancer (NSCLC)." (PMID 39681089, 2024). "ALK rearrangement is called the ‘diamond mutation’ in non‐small cell lung cancer (NSCLC)." (PMID 36423218, 2023). "The ALK F1174C/L/V mutation is a secondary acquired resistance to crizotinib in lung cancer." (PMID 38274094, 2023). "These traits might shed light on the biological mechanisms underlying the relatively aggressive nature of lung cancers with ALK rearrangements and suggest potential therapeutic approaches to overcome ALK inhibitor resistance and stop EMT-mediated metastasis." (PMID 36821071, 2023). "Decisions about targeted therapy, such as choosing certain tyrosine kinase inhibitors for individuals with epidermal growth factor receptor (EGFR) or anaplastic lymphoma kinase (ALK) mutations in lung cancer mutations, might be aided by ctDNA analysis." (PMID 37719630, 2023). "Similarly, PD-L1 expression and CD8+ T cells infiltration have a clinical relationship in lung cancer patients with ALK-rearranged and EGFR-mutated tumors." (PMID 36874015, 2023). "Non-small cell lungcancer (NSCLC) contributes to 80–85% of all lung cancer cases.Rearrangements in the genes encoding for anaplastic lymphoma kinase (ALK) andv-ros UR2 sarcoma virus oncogene homolog 1 (ROS1) are observed in 2–7% and1–2% of NSCLC samples, respectively." (PMID 39077026, 2023). "It is important to note that other relevant mutations typically associated with lung cancer (such as ALK, ROS1, RET, FGFR1, ERBB2, etc.)have been found with frequencies compatible with previously published data, but without a significant difference between subgroups." (PMID 37173325, 2023). "However, evidence from ALK fusion-positive lung cancer has shown that resistance to ALK inhibition occurs during the therapy, causing a relapse within several years." (PMID 37765276, 2023).
lung cancer (continued). "In addition, numerous lung-cancer-related mutations (e.g., in ALK, EGFR, and pmKRAS) as well as the loss of heterozygosity, microsatellite instability, and gene methylation, are also readily detected in these cfDNA." (PMID 37371825, 2023). "In conclusion, we used the state-of-the-art mass spectrometry platforms to characterize the cell surface N-glycome, proteome, and glycan distribution maps of a cohort of Filipino lung cancer samples (n = 5), who were previously characterized clinically for ALK and EGFR mutations." (PMID 36900350, 2023). "ALK is a receptor tyrosine kinase linked to neuroblastoma and lung cancer susceptibility." (PMID 36910592, 2023). "Lung cancer patients with ALK-rearrangement or EGFR mutations showed a poor response to ICIs." (PMID 36874015, 2023). "Moreover, pre-treatment vimentin expression in clinical specimens obtained from patients with ALK-rearranged lung cancer was associated with poor ALK-TKI treatment outcomes." (PMID 35042943, 2022). "Fusion of DYSF with the ALK gene has been found to be associated with advanced lung cancer." (PMID 35923697, 2022). "We designed in vitro experiments in this study to reduce and eliminate residual cancer cells maintained by treatment-induced adaptive reprogramming using three ALK-rearranged lung cancer cell lines with different EML4-ALK variants (H3122, H2228, and A925L cells)." (PMID 35228642, 2022). "Considering that lung cancer consists of heterogeneous tumors carrying distinct targetable driver gene mutations such as KRAS, EGFR, ALK, umbrella study can be perfectly implemented for lung cancer studies to explore the efficacy of different targeted drugs for patients with lung cancer." (PMID 36591460, 2022). "Anaplastic lymphoma kinase (ALK) gene rearrangements are a major hallmark of lung cancer." (PMID 36230484, 2022). "Because our cases are mainly lung cancer, digestive system tumor, and breast cancer, it is possible that the patient has a higher risk of developing a second cancer when pathological mutations in ALK and PTEN exist simultaneously." (PMID 36128740, 2022). "Finally, the understanding of risk factors for developing an ALK lung cancer remains primitive and extrapolated from the evidence from non-smoker-related long cancers broadly." (PMID 36003760, 2022). "The simultaneous discovery that autologous TILs for cell therapy are generally safe and clinically active in a subset of patients with advanced NSCLC might represent a novel therapeutic strategy for ALK mutated advanced lung cancer." (PMID 36591504, 2022). "Likewise, a study involving 7858 lung cancer patients which compared mutations between patients aged ≤45 vs >45 years observed a higher prevalence of ALK, ROS1 and RET fusions, ERBB2 exon-20 insertions and EGFR exon-19 deletions in younger patients." (PMID 36263208, 2022). "Plasma sequencing using next-generation sequencing is an emerging companion diagnostic technology for various indications such as BRCA1/2 testing in ovarian cancer, ALK rearrangements in lung cancer and PIK3CA gene mutations in breast cancer patients eligible for treatment with alpelisib." (PMID 36428589, 2022). "Besides EGFR, ALK, KRAS, ROS1, c-MET, and PIK3CA have been implicated as a driver of NSCLCs, such as crizotinib for ALK‐positive lung cancer patients." (PMID 36110964, 2022). "However, in ALK-rearranged lung cancer, the molecular mechanisms underlying residual tumors remain largely unexplored." (PMID 35228642, 2022). "In addition to detection of EGFR mutation, ALK rearrangements have been assessed in ctDNA of lung cancer patients." (PMID 35127511, 2021). "However, relapse due to acquired ALK inhibitor resistance caused by secondary ALK mutations often occurs in lung cancer patients." (PMID 34591871, 2021). "ALK gene mutations also have reference significance for the prognosis of lung cancer." (PMID 34596344, 2021).
lung cancer (continued). "In addition to EGFR mutations, ctDNA testing was also used for monitoring response or resistance to ALK inhibitors therapy in patients with lung cancer via identification of appearance of ALK variations, including ALK point mutations and rearrangements." (PMID 34422670, 2021). "Break-apart ALK FISH assay was approved by the FDA as a companion diagnostic for detecting ALK rearrangements in lung cancer patients who may benefit from treatment of ALK tyrosine kinase inhibitor therapy using ≥ 15% as a cutoff value." (PMID 33106918, 2021). "Hence, ALK rearrangement has emerged as the second most studied targetable mutation in order to develop a novel treatment approach to lung cancer." (PMID 35127511, 2021). "Over the past few years, the introduction of the epidermal growth factor receptor (EGFR), tyrosine kinase inhibitors (TKIs), and anaplastic lymphoma kinase (ALK)-based target therapy dramatically improved the therapeutic efficacy for lung cancer patients with specific gene mutations." (PMID 34307450, 2021). "For instance, an insurer might refuse to pay for an ALK inhibitor for a patient with colon cancer, even though the patient has the same mutation that drives lung cancer, but the drug is only approved for lung cancer tumors." (PMID 32284690, 2020). "In ALK-rearranged lung cancer, the underlying mechanisms and key factors by which a subpopulation of cancer cells escapes eradication after the inhibition of ALK remain unclear." (PMID 31900393, 2020). "Since the discovery of actionable activating epidermal growth factor receptor (EGFR) mutation and anaplastic lymphoma kinase (ALK) rearrangement in lung cancer, thoracic oncologists have led the way in comprehensive genomic profiling (CGP) of solid malignancies for precision medicine." (PMID 32478891, 2020). "Furthermore, mutation status (EGFR/ALK) in lung cancer and receptor status (ER/PR/HER2) in breast cancer also exhibit diversity in their response to radiotherapy." (PMID 32733787, 2020). "ALK R1275Q has an uncertain pathogenic significance in lung cancer." (PMID 32441866, 2020). "The aim of this study was to explore the predictive value of carcinoembryonic antigen (CEA), squamous cell carcinoma antigen (SCCAg), and neuron‐specific enolase (NSE) in the prediction of anaplastic lymphoma kinase (ALK) mutations in advance stage non‐small cell lung cancer (NSCLC)." (PMID 31489711, 2020). "Consistently, in NPM-ALK+ ALCL, as in EML4-ALK lung cancers and ALK-mutated neuroblastoma, a synergistic activity of ALK and mTOR inhibition had been described, although the authors did not investigate the involvement of autophagy associated with cell death in these settings." (PMID 33066037, 2020). "It has been speculated that NGS assays will become first line of methods for ALK status testing, together with testing many other mutations in lung cancer." (PMID 31412611, 2019). "As the most common sensitive gene mutations for lung cancer, a fusion gene between the anaplastic lymphoma kinase (ALK) gene and echinoderm microtubule associated protein-like 4 (EML4) was identified in 3% to 7% of unselected NSCLC patients, and further proved to be a potent oncogenic driver." (PMID 30658713, 2019). "However, sequential treatment of ALK-positive lung cancer with several ALK inhibitors including lorlatinib can select for compound ALK mutations with high-level resistance." (PMID 31452835, 2019). "Interestingly, we found that FAM83A but not FAM83B was downregulated in tumors bearing KRAS mutations as the EGFR mutation, KRAS mutation, and ALK rearrangement are largely mutually exclusive events in lung cancer." (PMID 31242643, 2019).
lung cancer (continued). "In the past ten years, big progress has been achieved in the treatment of LUAD with targeted lung cancer therapy such as drugs targeting the epidermal growth factor receptor (EGFR) mutation or the anaplastic lymphoma kinase (ALK)-rearranged NSCLC patients group." (PMID 31811110, 2019). "Besides, recent data suggest that ALK rearrangements occur more frequently in younger NSCLC patients compared to older patients with lung cancer, whereas KRAS mutations appear to be less frequent in the younger patient cohort." (PMID 31386689, 2019). "Some researchers have successfully detected the ALK and PD-L1 gene mutations in lung cancer." (PMID 31552169, 2019). "Although there is no NGS-based assay approved by the FDA as a first line method for determining ALK status yet, this powerful methodology, also called massively parallel sequencing, has been changing the diagnostic field dramatically, in both lung cancer and all other diseases." (PMID 31412611, 2019). "Therefore, further studies using a larger panel with various types of lung cancer cell lines and tissues would be useful to elucidate the causes of discordance in clinical ALK or ROS1 IHC tests." (PMID 30943926, 2019). "In addition, lung cancer, melanoma, and breast cancer with high BM probability have respective molecular mechanisms, such as ALK rearrangement, BRAF mutation, and D1‐CDK4/6 complex formation." (PMID 29992751, 2018). "Moreover, a gatekeeper mutation in the active kinase domain (L1196 M) renders ALK-positive lung cancer cells resistant to Crizotinib therapy." (PMID 29304828, 2018). "Because larger mutation screenings—including RAS, BRAF, MET (mutations, amplifications), ERBB2 (mutations, amplifications), ALK (mutations) and ROS (mutations)—were shown to be useful in the management of lung cancer patients, targeted NGS is progressively replacing single gene testing methods." (PMID 29890761, 2018). "The most prominent example is ALK, which was initially identified in anaplastic large cell lymphoma and later found in a significant share of neuroblastoma patients and in high frequency in lung cancer with activating mutation." (PMID 30171420, 2018). "Over the last decade, clinical management and treatment of lung cancer patients has become more dependent on molecular classification using “driver” mutations that occur in genes, such as anaplastic lymphoma kinase (ALK), epidermal growth factor receptor (EGFR), and c-Ros oncogene 1 (ROS1)." (PMID 29300322, 2018). "In addition to co-alterations in coding genes in ALK+ lung cancer, studies have shown a unique signature of non-coding microRNA expression associated with ALK rearranged lung cancer." (PMID 29189709, 2017). "Second generation ALK inhibitors including ceritinib, alectinib, and brigatinib target both therapy-naïve and crizotinib-resistant ALK positive lung cancers with acquired ALK mutations, and next generation ALK inhibitors are in various stages of clinical trials." (PMID 29189709, 2017). "ALK fusions created by gene translocations and rearrangements are associated with many types of cancer, including large cell lymphomas, inflammatory myofibrilastic tumours and non‐small cell lung cancer." (PMID 29055036, 2017). "The association we found between EMT molecular signatures and ALK rearrangements in NSCLC is consistent with the frequent observation of the loss of E-cadherin associated with vimentin expression in ALK-rearranged lung cancer compared with other NSCLC genotypes." (PMID 27119231, 2016). "Interestingly, a chromosomal translocation-induced ALK activation has been identified in 3–5% of non–small cell lung cancer (NSCLC) patients, and is clinically linked to a more aggressive phenotype." (PMID 26370727, 2015).